NEIL2 (nei like DNA glycosylase 2)
Description:
Involved in base excision repair of DNA damaged by oxidation or by mutagenic agents. Has DNA glycosylase activity towards 5-hydroxyuracil and other oxidized derivatives of cytosine with a preference for mismatched double-stranded DNA (DNA bubbles). Has low or no DNA glycosylase activity towards thymine glycol, 2-hydroxyadenine, hypoxanthine and 8-oxoguanine. Has AP (apurinic/apyrimidinic) lyase activity and introduces nicks in the DNA strand. Cleaves the DNA backbone by beta-delta elimination to generate a single-strand break at the site of the removed base with both 3'- and 5'-phosphates.
Synonyms: NEH2; FLJ31644; MGC2832; MGC4505; NEI2
Tractability: PROTAC: ubiquitination databases record sites on it.
Target class: Enzyme; Hydrolase
Gene: Protein-coding gene on chromosome 8 (11,769,639 to 11,787,345, forward strand). Ensembl gene ENSG00000154328.
Subcellular location: Nucleus
Subcellular location (Human Protein Atlas): Nucleoplasm; Vesicles
Pathways (Reactome):
DNA Repair: APEX1-Independent Resolution of AP Sites via the Single Nucleotide Replacement Pathway; Cleavage of the damaged pyrimidine; Recognition and association of DNA glycosylase with site containing an affected pyrimidine
Gene Ontology:
Molecular function: protein binding; DNA N-glycosylase activity; class I DNA-(apurinic or apyrimidinic site) endonuclease activity; damaged DNA binding; DNA-(apurinic or apyrimidinic site) endonuclease activity; hydrolase activity, hydrolyzing N-glycosyl compounds; microtubule binding; nucleic acid binding; zinc ion binding
Biological process: depyrimidination; base-excision repair
Cellular component: nucleoplasm; nucleus; cytoplasm; microtubule cytoskeleton; mitotic spindle
Genetic constraint (gnomAD): Loss-of-function variants: 28 observed, 24.49 expected, observed/expected ratio (o/e) 1.14, 90% interval 0.85 to 1.57. The synonymous counts are far from expectation, so gnomAD's model fits this gene poorly and the ratio says little. Missense variants: 583 observed, 425.77 expected, observed/expected ratio (o/e) 1.37, 90% interval 1.28 to 1.47. Synonymous variants: 229 observed, 172.63 expected, observed/expected ratio (o/e) 1.33, 90% interval 1.19 to 1.48.
Homologues: Orthologues: chimpanzee NEIL2 (99% identical), macaque NEIL2 (92% identical), rabbit NEIL2 (75% identical), guinea pig NEIL2 (74% identical), mouse Neil2 (73% identical), rat Neil2 (73% identical), pig NEIL2 (72% identical), dog NEIL2 (64% identical). Paralogues in human: NEIL3 (22% identical), NEIL1 (19% identical).
Diseases named in the same sentence as NEIL2 in open-access papers:
NEIL2 is named in the same sentence as 52 diseases in open-access papers, as found by Europe PMC text mining. Sharing a sentence is not in itself a finding about the gene and the disease. The quoted sentences say what the papers report.
lung carcinoma (7 papers, 2014 to 2025). "This particular study showed that the R257L mutant of NEIL2 reduces the DNA glycosylase activity, weakens the ability of DNA damage repair, induces gene mutations, and eventually leads to lung cancer." (PMID 32626527, 2020). "It has also been shown that knock out of NEIL2 increased the accumulation of spontaneous mutations, and a variant of NEIL2 was observed in lung cancer samples." (PMID 29696001, 2018). "Increased risk of lung cancer is associated with a functionally impaired polymorphic variant of the human DNA glycosylase NEIL2." (PMID 26357532, 2015). "Cases with mutations (assuming loss of function) or CNV alterations (all CNV loss, other than 1 CNV gain lung cancer case) in NEIL2 displayed decreased OS in liver hepatocellular carcinoma and decreased DFS in bladder urothelial and lung squamous cell carcinoma." (PMID 27004405, 2016). "NEIL2 polymorphisms may affect the development and treatment sensitivity of lung cancer." (PMID 40761744, 2025). "In lung cancer, NEIL2 acts as a tumor suppressor, and the level of NEIL2 is extremely low in half of cancer tissues." (PMID 40761744, 2025). "Taken together, NEIL1 and NEIL2 function as tumor suppressors and their abnormal expression can lead to the development of lung cancer and drug resistance." (PMID 40761744, 2025). "We also identified a novel polymorphic NEIL2 variant R257L that possesses reduced total BER activity towards oxidized bases and is present at significantly higher levels in lung cancer patients than in controls in certain human populations." (PMID 24595271, 2014). "Impaired NEIL2 expression in sidestream smoke-exposed nonsmokers may cause the accumulation of genomic DNA mutations, which could lead to sidestream smoke-induced lung cancer." (PMID 40761744, 2025). "Lower doses of lycopene improve the levels of NEIL1, NEIL2, and NEIL3 in cigarette smoke-induced A549 human lung cancer epithelial cells." (PMID 40761744, 2025). "Lycopene masked lung cancer proliferation by suppressing oxidative stress as well as by elevating 8‐oxo guanine DNA glycosylase (OGG1), connexin‐43 (Cx43), and Nei‐like DNA glycosylases (NEIL1, NEIL2, and NEIL3) expression." (PMID 40661795, 2025). "Taken together, our data strongly suggest that decreased repair of oxidative DNA base lesions due to an impaired NEIL2 expression in non-smokers exposed to SSS would lead to accumulation of mutations in genomic DNA of lung cells over time, thus contributing to the onset of SSS-induced lung cancer." (PMID 24595271, 2014). "Unlike NEIL1 and NEIL2, NEIL3 functions as an oncogenic factor in lung cancer." (PMID 40761744, 2025).
breast carcinoma (6 papers, 2014 to 2025). "Given the heterogeneity of tumor samples, cell lines derived from the breast cancer tissues should also be useful sources of experimental material for investigating the relationship between NEIL2 expression and the mutational processes in tumors." (PMID 31904337, 2020). "We show here that elevated expression of the bifunctional DNA glycosylase, NEIL2, sensitizes breast cancer cells to A3B-mediated mutations and double-strand breaks (DSBs) by perturbing canonical base excision repair (BER)." (PMID 31904337, 2020). "The strongest evidence of association was observed for rs1466785 in the NEIL2 gene (HR: 1.09, 95% CI (1.03–1.16), p = 2.7×10−3) for association with breast cancer risk in BRCA2 mutation carriers." (PMID 24698998, 2014). "In addition, we found a positive correlation between U/G repair-induced mutations and the relative NEIL2 expression (qRT-PCR data) in the four breast cancer cell lines." (PMID 31904337, 2020). "High levels of NEIL2 expression can maintain low levels of ROS and stemness in breast cancer stem cells." (PMID 40761744, 2025). "In breast cancer, the binding of Sp1 to the NEIL2 promoter is boosted by low ROS, thereby promoting NEIL2 transcription and enhancing BER." (PMID 40761744, 2025). "Polymorphisms ERCC3/XPB, NEIL-2, NTH-1, and FEN-1 have been studied in lung, gastric, lung, and breast cancer." (PMID 38892180, 2024). "NEIL2 is involved in the regulation of cellular ROS concentrations in breast cancer stem cells." (PMID 40761744, 2025). "NEIL2 expression is elevated in breast cancer stem cells, leading to doxorubicin resistance." (PMID 40761744, 2025). "Furthermore, increased NEIL2 expression enhances the sensitivity of breast cancer cells to double-strand breaks and apolipoprotein B mRNA editing enzyme catalytic subunit 3 (APOBEC3) deaminase-mediated mutations by interfering with BER." (PMID 40761744, 2025). "In conclusion, NEIL2 may provide new perspectives for breast cancer treatment, and NEIL3 may have a role in the onset and progression of breast cancer." (PMID 40761744, 2025). "Loss of NEIL2 leads to endocrine therapy resistance via dysregulation of the G1-S transition, and miRNA regulation of NEIL2 may mediate the prognosis of hormone-treated breast cancer." (PMID 40761744, 2025). "Additionally, it has been shown that the bifunctional DNA glycosylase NEIL2, which is upregulated in the breast cancer cell line Hs578T, outcompetes APE1 at AP sites and sensitizes breast cancer cells to APOBEC3 deaminase-mediated mutations." (PMID 34445469, 2021). "We further show that purified NEIL2 disrupts canonical BER by outcompeting APE1 for AP sites, thereby providing a possible mechanistic explanation for how this instance of DNA repair dysregulation contributes to the mutational landscape in breast cancer cells." (PMID 31904337, 2020). "Here we demonstrate in breast cancer cell lines that elevated expression of NEIL2, a bifunctional glycosylase normally involved in oxidative base excision repair, facilitates A3B-mediated mutations during U/G mismatch repair and induces double-strand breaks (DSBs) in genomic DNA." (PMID 31904337, 2020). "The minor allele of NEIL2-rs1466785 was associated with increased breast cancer risk in BRCA2 mutation carriers; moreover, when considering the genotype-specific risks observed that the best fitting model was the dominant one." (PMID 24698998, 2014). "NEIL2 and NEIL3 play a role in the development and progression of breast cancer." (PMID 40761744, 2025).
gastric cancer (4 papers, 2020 to 2025). A primary or metastatic malignant neoplasm involving the stomach. "Helicobacter pylori infection is closely associated with gastric cancer and NEIL2 expression is markedly reduced by Helicobacter pylori infection." (PMID 40761744, 2025). "In addition, the NEIL2 SNP is potentially associated with gastric cancer, esophageal adenocarcinoma, and Barrett’s esophagus risk." (PMID 40761744, 2025). "By inhibiting NEIL2, H. pylori hinders DNA damage repair mechanisms, amplifies inflammation and facilitates gastric cancer development." (PMID 40033009, 2025). "Studies have further demonstrated a correlation between decreased NEIL2 levels in human gastric tissue and the progression of gastric cancer." (PMID 40033009, 2025). "It was reported that the level of NEIL2 is significantly decreased in Helicobacter pylori-positive gastric cells, and lower NEIL2 expression correlated with a lower probability of survival of gastric cancer." (PMID 37423306, 2023). "Moreover, Helicobacter pylori, a bacterium with the potential to induce gastric cancer, is also inhibited by NEIL2." (PMID 40033009, 2025).
bladder cancer (3 papers, 2012 to 2019). "Since either miRNAs showed similar inhibitory effects on both wildtype and variant genotypes, it is possible that rs4639 may not be the causative variant but functions as a tagging SNP for other polymorphisms that may contribute to bladder cancer recurrence by altering NEIL2 expression or function." (PMID 22701660, 2012). "NEIL2 is involved in DNA repair mechanisms, and research suggest it influences malignancies beyond bladder cancer." (PMID 31681611, 2019).
colorectal cancer (3 papers, 2006 to 2020). A primary or metastatic malignant neoplasm that affects the colon or rectum. "As has been found in colorectal cancer, NEIL2 gene variants (R103Q, R103W, P123T, and R257L) are risk factors for colorectal cancer." (PMID 32626527, 2020). "This scenario is compatible with a previous paper reporting a germline NEIL2 variant that is a marker for risk and the progression of squamous cell carcinomas of the oral cavity and oropharynx and that is selectively found in familial colorectal cancer patients, but not in healthy controls." (PMID 27042257, 2016).
gastric adenocarcinoma (3 papers, 2016 to 2023). "Similarly, overexpressing NEIL2 in human gastric adenocarcinoma, AGS cells infected with the human coronavirus 229E strain significantly decreased IL6 transcript levels, concomitant with decreased expression of viral E-gene, when compared with control cells." (PMID 38071370, 2023).
lung adenocarcinoma (3 papers, 2014 to 2016). A carcinoma that arises from the lung and is characterized by the presence of malignant glandular epithelial cells. "The levels of NEIL2 were analyzed in a lung adenocarcinoma tissue microarray (33 cases and normal controls) by immunohistochemistry using affinity purified NEIL2 antibody." (PMID 24595271, 2014).
neuroblastoma (3 papers, 2014 to 2025). Neuroblastoma (NB) is the most common solid, extracranial childhood tumor. "Here, we report that NEIL2 is phosphorylated in the human neuroblastoma cell line SH-SY5Y, and that the protein is dephosphorylated in response to acute oxidative stress in this cellular model." (PMID 36829914, 2023). "In order to investigate whether NEIL2 is regulated by phosphorylation in cells, we expressed His-tagged NEIL2 in the human neuroblastoma SH-SY5Y cell line." (PMID 36829914, 2023). "We demonstrate that NEIL2 is phosphorylated by the two kinases cyclin-dependent kinase 5 (CDK5) and protein kinase C (PKC) in vitro and in human SH-SY5Y neuroblastoma cells." (PMID 36829914, 2023). "Co-localizations of NEIL2 with hnRNP-U with actively transcribed genes were confirmed by pulling down NEIL2-FLAG expressing AGS and neuroblastoma SK-N-BE2-(C) cells, followed by chromatin immunoprecipitation with hnRNP-U antibodies." (PMID 24705290, 2014).
Alzheimer disease (2 papers, 2009 to 2019). A progressive, neurodegenerative disease characterized by loss of function and death of nerve cells in several areas of the brain leading to loss of cognitive function such as memory and language. "Besides, the upregulated genes of both Neil1- and Neil2-deficient EBs + RA were significantly enriched for the pathway term ‘TYROBP causal network’, associated with late-onset Alzheimer’s disease." (PMID 31566562, 2019). "Two of these genes, NEIL2 and MSRA, are related to repair of oxidative damage, and CTSB has been suggested to play a role in Alzheimer's disease." (PMID 20011547, 2009).
Anxiety (2 papers, 2021 to 2022). Intense feelings of nervousness, tension, or panic often arise in response to interpersonal stresses. "As the hippocampus is one of the critical brain areas involved in anxiety as well as learning and memory, we assessed the effect of NEIL1 and/or NEIL2 deficiencies on hippocampal DNA integrity." (PMID 34857879, 2021). "The current study revealed an altered behavioral phenotype in mice deficient in both the NEIL1 and NEIL2 DNA glycosylases, shown as increased locomotor activity in the OF test and the EZM, reduced anxiety in the EZM, and improved learning ability in the MWM test." (PMID 34857879, 2021). "Moreover, the knockout of DNA glycosylases NEIL1 and NEIL2 causes dysregulation of genes that are relevant for synaptic function in CA1 and leads to reduced anxiety and improved learning in these animals that is potentially linked to changes in GABAergic signalling." (PMID 35907861, 2022).
CoV-2 infection (2 papers, 2022 to 2023). "Toward better understanding the mechanistic basis of how NEIL2 plays such a protective role against CoV-2 infection, we determined that NEIL2 specifically binds to the 5’-UTR of SARS-CoV-2 genomic RNA and blocks protein synthesis." (PMID 35665009, 2022).
lung disease (2 papers, 2021 to 2023). "We thus propose that intrapulmonary delivery of NEIL2, with its dual role in regulating inflammation and DNA repair, has strong potential as a therapeutic agent, especially for chronic inflammatory conditions such as asthma, chronic obstructive pulmonary disease, and other human lung diseases." (PMID 33932404, 2021).
Obesity (2 papers, 2023 to 2025). Accumulation of substantial excess body fat. "The methylation site cg12568669 which was reported in the previous section to be associated with obesity also impacted blood pressure in a similar pattern, namely, by changing the expression of NEIL2 and FDFT1 genes." (PMID 37274792, 2023). "POC5, ILRUN, FDFT1, and NEIL2 mediated the impact of CpG sites on obesity through metabolic pathways." (PMID 37274792, 2023). "Integration of methylation data with gene expression profiles revealed putative mediators of these relationships—genes such as ILRUN, POC5, FDFT1, NEIL2, and others—whose methylation changes may affect metabolic pathways and contribute to obesity pathogenesis." (PMID 41303351, 2025). "We found the methylation site, cg12568669 within FDFT1 gene contributes to obesity by changing the expression of FDFT1 and the nearby gene NEIL2." (PMID 37274792, 2023).
oral squamous cell carcinoma (2 papers, 2020). "The CC genotype at the 4102971 locus of the NEIL2 gene significantly increased the incidence of oral squamous cell carcinoma, especially advanced oral squamous cell carcinoma." (PMID 32626527, 2020).
squamous cell carcinoma (2 papers, 2016 to 2018). A carcinoma arising from squamous epithelial cells. "Furthermore, functional variants of NEIL2 have been linked to greater risk of squamous cell carcinoma in the oral cavity and oropharynx, making it a possible marker for risk to and progression of squamous cell carcinoma in the oral cavity and oropharynx." (PMID 29696001, 2018).
viral infection (2 papers, 2022 to 2023). "Collectively, these data strongly suggest that the maintenance of basal NEIL2 levels is critical for the protective response of hosts to viral infection and disease." (PMID 38071370, 2023). "It is imperative that NEIL2 coordinates with other host factors to mount an elevated defense against viral infection." (PMID 38071370, 2023).
Age-related cataract (1 paper, 2023). A type of cataract (opacification of the lens) that forms during the course of aging. "It is shown to bind to 3ʹUTR of NEIL2 (Nei Like DNA Glycosylase 2) to contribute to age related cataracts by interfering with the DNA repair mechanism." (PMID 37310937, 2023).
cervical carcinoma (1 paper, 2020). A carcinoma arising from either the exocervical squamous epithelium or the endocervical glandular epithelium. "The reduced levels of DNA repair activity in cells featuring the NEIL2 rs8191664 (R257L) missense mutation can induce genomic instability that ultimately leads to the initiation of cervical carcinoma." (PMID 32198476, 2020). "Furthermore, we also detected the expression of the NEIL2 gene in different genotypes of cervical cancer cells at the mRNA and protein level to investigate the relationship between SNP genotypes and gene expression." (PMID 32198476, 2020). "In addition, the correlation between SNP loci in NEIL1 and NEIL2 and susceptibility to cervical carcinoma has not been studied so far." (PMID 32198476, 2020).
oral cancer (1 paper, 2020). "A recent study found that the SNP in the 5′- regulatory region of the NEIL2 gene was associated with the risk of oral cancer." (PMID 32626527, 2020).
ovarian carcinoma (1 paper, 2014). A malignant neoplasm originating from the surface ovarian epithelium. "In summary, we have identified at least two SNPs, rs1466785 and rs2304277, in the DNA glycolylases NEIL2 and OGG1, potentially associated with increased breast and ovarian cancer risks in BRCA2 and BRCA1 mutation carriers, respectively." (PMID 24698998, 2014).
polycystic ovary (1 paper, 2024). "The GATA4/NEIL2 locus also has previous links with ovulatory dysfunction and polycystic ovary morphology." (PMID 38408933, 2024).
prion disease (1 paper, 2016). A transmissible disease that is caused by a protein that is able to induce abnormal folding of normal cellular proteins, leading to characteristic spongiform brain changes, which are associated with neuronal loss without an inflammatory response. "There was a significant decrease in expression at either onset or end-stage or both for some of the DNA glycosylases (Neil1, Neil2 and Ogg1) in wild-type mice, demonstrating a lack of compensatory up-regulation of brain DNA glycosylases in prion disease." (PMID 27886261, 2016). "Despite the fact that DNA repair capacities appears to be gradually overwhelmed during prion disease, neither this nor the lack of Neil3 elicit any compensatory increase in expression levels of other DNA glycosylases with overlapping substrate specificities (i.e. Neil1 and Neil2)." (PMID 27886261, 2016).